CD4 (CD4 molecule)
Diseases named in the same sentence as CD4 in open-access papers (continued):
Sharing a sentence is not in itself a finding about the gene and the disease.
peritonitis (15 papers, 2013 to 2023). Inflammation of the peritoneum (tissue that lines the abdominal wall and covers most of the organs in the abdomen). "When the baseline CD4 count was below 200 cells/μL, the peritonitis rate rose to 3.69 episodes/person-years (HR 4.54, 95% CI 2.35–8.76, P < 0.001), while a baseline CD4 count above 350 cells/μL was associated with a peritonitis rate of 1.60 episodes/person-years (HR 2.10, CI 1.39–3.15, P = 0.001)." (PMID 28158991, 2017). "When the baseline CD4 count was below 200 cells/μL, the peritonitis rate rose to 3.690 episodes/person-years (HR 4.54, 95% CI 2.35–8.76, P < 0.001), while a baseline CD4 count above 350 cells/μL was associated with a peritonitis rate of 1.599 episodes/person-years (HR 2.10, CI 1.39–3.15, P = 0.001)." (PMID 28158991, 2017). "Indeed, it was shown that an increase in the CD4+ cells in the peritoneal exudate of PD patients correlated with improved peritonitis outcomes and may be linked with the mobilization of lymphocytes." (PMID 33074093, 2021). "Reductions in peritonitis risk in the present cohort are likely mediated by use of ART, as a result of which two-thirds of PLWH included in this series had a CD4 count at dialysis initiation above 200 cells/mm3." (PMID 37293605, 2023). "We first used a well-established model of peritonitis induced by TNF-α to assess CD4+ T cell and Gr1+ neutrophil recruitment." (PMID 34156982, 2021). "In this study, we evaluated the humoral immune response and CD4+ T cell-mediated immune responses in a mouse peritonitis model." (PMID 29483570, 2018). "A baseline CD4 count <200 cells/μL increased the hazards for peritonitis more than 4-fold compared to HIV-negative CAPD patients (3.69 episodes/person-years, HR 4.54, P < 0.001)." (PMID 28158991, 2017). "A baseline CD4 count above 350 cells/μL was associated with a 2-fold increased hazard for peritonitis (1.60 episodes/person-years, HR 2.10, P = 0.001), further highlighting the inherent risk associated with HIV infection even with higher CD4 counts." (PMID 28158991, 2017). "In the peritonitis model, IL-17A neutralization and CD4+ effector T cell-depletion equally increased the bacterial load in kidneys of mice vaccinated with 4C-Staph/T7-alum, suggesting that Th17 are the main source of IL-17A in these settings." (PMID 26812180, 2016). "RAGE promotes leukocyte recruitment in a mouse model of peritonitis and Cyclophilin A is released from necrotic liver cells and can direct activated CD4+ T cell migration in vitro and in vivo." (PMID 24244314, 2013). "In this study, we show that adjuvanting a multivalent vaccine (4C-Staph) with MF59, an oil-in-water emulsion licensed in human vaccines, further potentiated antigen-specific IgG titers and CD4 T-cell responses compared to alum and conferred protection in the peritonitis model of S. aureus infection." (PMID 26441955, 2015). "Septic peritonitis did not induce significant changes of VISTA expression on either CD4+ or CD8+ T cells." (PMID 34366711, 2021). "Patients experiencing technique failure after an episode of acute peritonitis had marginally higher levels of calprotectin, MMP-8, sIL-6R, and transforming growth factor-β in their dialysis effluent as well as lower CD4+ : CD8+ T-cell ratios compared with uncomplicated cases." (PMID 28318629, 2017).
progressive multifocal leukoencephalopathy (15 papers, 2015 to 2025). Progressive multifocal leukoencephalopathy (PML) is a neurological disorder that damages the myelin that covers and protects nerves in the white matter of the brain. "The cause of CNS infections in HIV have been related to the CD4 lymphocyte count, of which a value below 200 has been described to predispose to cerebral toxoplasmosis, progressive multifocal leukoencephalopathy (PML), and cryptococcal meningitis." (PMID 34603192, 2021). "Treatment of MS patients with biological drugs designed to suppress the induction, migration, or function of CD4+ T cells, such as natalizumab, come with an increased risk of infection, in particular progressive multifocal leukoencephalopathy (PML)." (PMID 26441960, 2015). "Cell adhesion inhibitors (natalizumab) compromise the cellular (CD4 and CD8 lymphocytes) surveillance in the CNS and may predispose not only to progressive multifocal leukoencephalopathy, a John Cunningham (JC) virus, but also to herpetic and varicella zoster encephalitis." (PMID 35976311, 2022). "Also, a lower frequency of CD4+ CM T cells was reported in acute progressive multifocal leukoencephalopathy (PML) that was preserved in patients with a fatal PML outcome." (PMID 36169248, 2022). "In human JC polyomavirus infection, when CD4+ T cells decrease due to AIDS, progressive multifocal leukoencephalopathy (PML) may develop as a brain lesion." (PMID 34502427, 2021). "We present two cases of recurrent progressive multifocal leukoencephalopathy (PML) in patients with long standing virally suppressed human immunodeficiency virus (HIV) and normal CD4+ T cell count who were taking stable regimens of highly active antiretroviral therapy (HAART)." (PMID 26727910, 2016).
prostatitis (15 papers, 2013 to 2025). An infectious or non-infectious inflammatory process affecting the prostate gland. "In this review, we discuss the potential role of P. acnes in the development of BPH and PCa and highlight the importance of regulatory T CD4(+)FoxP3(+) (Treg) and Th17 cells in response to P. acnes infection in the context of both prostate diseases." (PMID 36012113, 2022). "These proinflammatory factors can induce the differentiation of CD4+ cells, the most common immune cells in chronic prostatitis, and mediate inflammatory responses and pain." (PMID 32595732, 2020). "Therefore, in this review, we discuss the potential role of P. acnes in the development of BPH and PCa and highlight the importance of regulatory T CD4(+)FoxP3(+) (Treg) and Th17 cells in response to P. acnes infection in the context of both prostate diseases." (PMID 36012113, 2022). "Examination of the non-sorted cells from the testis tumor showed that most cells (including the EGFP-positive cell) were CD4-positive, with high or low level." (PMID 24359464, 2013).
rheumatic diseases (15 papers, 2008 to 2026). "It is believed that the presence of inflammatory, memory CD4+ and plasma B cells resistant for conventional therapy in BM may cause the reason why chronic diseases, including rheumatic diseases, are still incurable today." (PMID 32111105, 2020). "In the present study, we confirmed that CD4 + T cells are a correlated factor for lung involvement in children with rheumatic disease." (PMID 35987688, 2022). "Based on our cohort of patients with rheumatic diseases, elevated ESR and CD4/CD8 ratio appeared to be significantly associated with pulmonary involvement in the univariate and multivariate logistic regression." (PMID 35987688, 2022). "As the IL-17-producing cells, clinical relevance of CD4+CD161+ T cells has been addressed in several rheumatic diseases." (PMID 26436101, 2015). "Nonetheless, current studies of CD4+CD25high regulatory T cells in rheumatic diseases provide the scientific foundation for further research." (PMID 19046457, 2008). "Nevertheless, the manipulation of CD4+CD25high regulatory T cell function shows great promise as a novel therapeutic option in autoimmune and rheumatic diseases." (PMID 19046457, 2008). "Little is known of the mechanisms of this control; however, the alterations in distribution and function of CD4+CD25high regulatory T cells in autoimmune and rheumatic diseases suggest a role for the therapeutic use of these cells." (PMID 19046457, 2008). "Perhaps this CD27+ CD4 subset is linked to a more general state of inflammation in rheumatic diseases, rather than an axSpA-specific process." (PMID 37306812, 2023). "The high-dimensional immune profiling study presented here deeply phenotyped in parallel synovial CD8+ and CD4+ CD69+CD103+ TRM cells in two rheumatic diseases and identified them as a heterogeneous population characterized by multiple distinct phenotypes and functions." (PMID 37195862, 2023). "Therefore, our study highlights the investigation of CD4 T cells and their development in early rheumatic disease, potentially using CD27 to identify subsets of interest in comparison to controls." (PMID 37306812, 2023). "The work on CD4+CD25high regulatory T cells in other rheumatic diseases is limited to date." (PMID 19046457, 2008). "In rheumatic diseases, most studies have focused on CD4+CD25high regulatory T cells, while the roles of other regulatory T cell types remain unclear." (PMID 19046457, 2008). "Among lymphocytes, in addition to CD8+ T cells, CD4+ T cells, and B cells, growing attention has been directed toward some unconventional T-cell subsets, such as TCRαβ+ double-negative T (DNT) cells, based on findings in several autoimmune/rheumatic diseases." (PMID 41511342, 2025). "Current data indicate that reduced numbers of circulating CD4+CD25high regulatory T cells is not a general finding in rheumatic diseases, while reduced function is more commonly found." (PMID 19046457, 2008). "Unfortunately, mouse models on CD4+CD28− T-cells are not available so far, and therefore we have to rely on in vitro experiments as well as clinical studies to investigate the role of these cell subsets in rheumatic diseases." (PMID 29472917, 2018).
scleroderma (15 papers, 2014 to 2024). Scleroderma is a rare autoimmune connective tissue disorder characterized by abnormal hardening of the skin and, sometimes, other organs. "The immunofluorescence staining results showed that the proportion of IL-17A+/CD4+ cells was higher in hypertrophic scar and scleroderma tissues than in normal control tissues." (PMID 39872534, 2024). "We identified that scleroderma skin grafts contained both skin and bone marrow–derived human CD4 and CD8 T cells along with human endothelial cells and pericytes." (PMID 37669366, 2023). "Altogether, our results suggest that activation of scleroderma skin–derived CD4 and CD8 T cells is decreased by HSC engraftment." (PMID 37669366, 2023). "Scleroderma is characterized by progressive tissue fibrosis, with skin most commonly affected by edema and perivascular CD4+ and CD8+ lymphocytic infiltrations." (PMID 24443980, 2014). "Thus, scleroderma skin grafts retained human CD4 and CD8 T cells and pericytes but lost human fibroblasts." (PMID 37669366, 2023). "The ability of T cells to produce sIL6Ra suggests that both macrophages and CD4 T cells may be relevant cell types in promoting fibrosis in patients with scleroderma." (PMID 37669366, 2023). "In a recent publication we reported that the scurfy phenotype closely resembles scleroderma as scurfy skin has a higher collagen content and the inflammatory response is driven by CD4+ T cells with Th2 differentiation and alternatively-activated (M2) macrophages." (PMID 31068947, 2019). "Other studies demonstrated that ASC administration was sufficient to attenuate BLM-induced scleroderma by suppressing the infiltration of CD4+ and CD8+ T cells and macrophages into the dermis, but it also reduced the frequency of CD4+ T cells and effector B cells in the spleens of SS mice." (PMID 34685439, 2021). "We cultured CD4+ T cells with the supernatant of pyroptotic BMDMs in vitro, and the resulting T cells had a stronger ability to secrete IL-17A, indicating that GSDMD-related pyroptosis in macrophages could promote T cells differentiate into Th17, which may contribute to skin fibrosis in scleroderma." (PMID 35396386, 2022).
septic shock (15 papers, 2009 to 2025). Shock caused by infection; frequently caused by gram negative bacteria, although some cases have been caused by other bacteria, viruses, fungi, and protozoa; characterized by fever, chills, tachycardia, tachypnea, and hypotension. "The septic shock samples exhibited increased infiltration of plasma cells, resting memory CD4+ T cells, follicular helper T cells, monocytes, M0 and M1 macrophages, eosinophils, and neutrophils." (PMID 41189212, 2025). "In contrast to our results and previous ones showing modulation of Th cell sub-populations in septic patients, Venet and coworkers recently showed that all CD4+T lymphocyte subsets were equally diminished in septic shock patients." (PMID 22693573, 2012). "We observed that septic shock patients displayed increased PD-1, PD-Ligand1 (PD-L1) and PD-L2 monocyte expressions and enhanced PD-1 and PD-L1 CD4+ T lymphocyte expressions at day 1-2 and 3-5 after the onset of shock in comparison with patients with trauma and healthy volunteers." (PMID 21418617, 2011). "Compared with healthy controls, the percentages of circulating PD-1/CD4+ T cells, PD-1/CD8+ T cells, and monocytes expressing PD-L1 were significantly higher in septic patients and septic shock patients (P < 0.05)." (PMID 27156867, 2016). "PD-1, PD-L1, and PD-L2 expressions were measured on circulating CD4+ lymphocytes, CD8+ lymphocytes (PD-1 only), and monocytes at D1-2 and 3-5 after the onset of septic shock." (PMID 21418617, 2011). "The number of circulating CD3+CD4+CD28+ T cells was significantly lower in surviving and nonsurviving patients with septic shock compared with healthy controls on admission and on day 3 of follow-up." (PMID 19243622, 2009).
T-cell acute lymphoblastic leukemia (15 papers, 2009 to 2024). Acute lymphoblastic leukemia of T-cell origin. "We next explored the methylation status of ESSEs in acute T cell leukemia cells (Jurkat) versus that of normal mature CD4+ or CD8+ T cells." (PMID 26886256, 2016). "Based on this study, we modeled a CD4+ T-cell, manipulated gene expression in immunocompromised versus competent settings, validated these manipulations in an in vivo murine model, and corroborated acute T-cell leukemia gene expression profiles in human beings." (PMID 25538703, 2014). "A total of 25% of cases of this group were represented as T-cell ALL which characteristically expressed CD5, surface CD3 (sCD3) and CD4/CD8 dichotomy markers." (PMID 39113054, 2024). "The uninfected cells that were tested included the acute T-cell lymphoblastic leukemia cell lines, Jurkat and CEM, as well as resting and anti-CD3/anti-CD28-activated primary CD4+ T-cells." (PMID 31251786, 2019). "The phenotypic profiles of our patients are close to those reported in literature for B-lineage ALLs; for the T-cell ALL subgroup, the blast cells express more CD1a, surface CD3, and CD4 while expressing less TdT." (PMID 20041009, 2009).
urinary tract infection (15 papers, 2014 to 2025). "Another study on factors associated with urinary tract infections among HIV-infected patients with low CD4 count, chronic hepatitis, and being female." (PMID 38820330, 2024). "It has been observed that those with low lymphocyte CD4+ counts (<200 cell/μl) are at significantly higher risk of asymptomatic bacteriuria and are therefore more likely to develop urinary tract infection." (PMID 29324763, 2018). "CD4+ count, combination of antiretroviral therapy (ART) drugs, and a history of hospitalization were risk factors for urinary tract infection." (PMID 38746741, 2024). "The incidence of bacterial infections, including urinary tract infection, was inversely correlated with CD4+ T cells." (PMID 38746741, 2024). "CD4+Tbet+IFN-γ+ and CD4+FoxP3+IL-10+ T cell populations were decreased in HbSS subjects with asymptomatic urinary tract infections." (PMID 34239376, 2021). "Urinary tract infections appear to be multifactorial in patients with HIV infections as CD4+ level declines." (PMID 30881531, 2019). "As confirmed by observational studies the incidence of various bacterial infections in HIV-infected patients, including urinary tract infections, is inversely correlated with lymphocyte CD4+ count." (PMID 29324763, 2018). "Being registered before/in 2007, infected through other than homosexual mode and female gender in our study increased the odds of urinary tract infection, while higher nadir lymphocyte CD4+ count was decreasing the odds of first urinary tract infection." (PMID 29324763, 2018). "Low CD4+ count <200 cells/μL, being single, and the presence of urinary tract infection symptoms can be used as predictors of UTI when planning for selective screening in areas where urine culturing is not routinely performed." (PMID 28255302, 2017). "Positive correlation between CD4+ count and urinary tract infection was detected and found statistically significant (r = 0.288 p > 0.01), whereas the viral load and urinary tract infection negatively correlated and showed statistically significant association (p < 0.01)." (PMID 38746741, 2024). "Moreover, CD4 level monitoring and therapeutics selection based on microbiological culture are quite advisable for the management of urinary tract infections of HIV patients." (PMID 38820330, 2024). "The incidence of urinary tract infections in HIV population is clearly related to infection and immune function, determined by lymphocytes CD4+ cells count." (PMID 29324763, 2018). "Patients with a urinary tract infection had an increased frequency of total T cells expressing TIM-3 and CD4+ T cells expressing CD127 compared to patients with a negative bacteria culture result (p=0.035 and p=0.025 respectively)." (PMID 26993768, 2016). "Urinary tract infections occur at increased rates among HIV-infected persons, and bacteriuria is more common in those with very low CD4 cell counts, which could explain our findings." (PMID 25485634, 2014).
aspergillosis (14 papers, 2011 to 2025). Aspergillosis is an infection, growth, or allergic response caused by the Aspergillus fungus. "In his study, we present the characteristics of an Iranian boy with SCBMS and CD4 deficiency, reporting the first case of aspergillosis associated with the NM_005219.5 c.3145C > T; p.R1049X variant of homozygous DIAPH1 loss." (PMID 36212620, 2022). "Future studies with more significant numbers of additional animals and various degrees of immunosuppression may be required to decipher the exact role of STAT3 deficiency in CD4+ T cells in susceptibility to aspergillosis in immunosuppressed mice." (PMID 33526558, 2021). "Due to the patient’s medical history and the evidence of PJI and pulmonary aspergillosis, an immunological assessment was performed, and a severe CD4-penia emerged: CD4+ was 1.06% (6 cell/μl, normal value 500–1000)." (PMID 37464267, 2023). "One case study reported a HIV patient who had a high CD4 count of 863 cells/mm3 who survived despite having pulmonary aspergillosis." (PMID 36354898, 2022). "Further subgroup analysis revealed a significantly higher mortality in aspergillosis group with CD4+ T cells count < 200 cell/μL (60.7 vs. 30.6%, P = 0.023)." (PMID 33537328, 2020). "In Aspergillus fumigatus infection, both CD4+ and CD8+ T cells mediate vaccine-induced protection from experimental aspergillosis." (PMID 26091522, 2015).
atrial fibrillation (14 papers, 2015 to 2025). A disorder characterized by an electrocardiographic finding of a supraventricular arrhythmia characterized by the replacement of consistent P waves by rapid oscillations or fibrillatory waves that vary in size, shape and timing and are accompanied by an irregular ventricular response. "The positive expression rate of PD-1 on CD4+ lymphocytes was significantly lower in patients in the atrial fibrillation group than in the control group (P < 0.01)." (PMID 35600045, 2022). "Upregulated CD8 T cell expression was also found in patients with postoperative atrial fibrillation (POAF), and another study found that loss of CD28 antigen in CD4 T cells may be a potential mechanism of AF." (PMID 38178669, 2024). "In addition, the atrial fibrillation risk (AF) of HIV patients, which is related to the lower CD4 count or (and) and the higher viral load, is higher than that of the non-HIV population." (PMID 37600062, 2023).